PLVAP (plasmalemma vesicle associated protein)
Description:
Endothelial cell-specific membrane protein involved in the formation of the diaphragms that bridge endothelial fenestrae. It is also required for the formation of stomata of caveolae and transendothelial channels. Functions in microvascular permeability, endothelial fenestrae contributing to the passage of water and solutes and regulating transcellular versus paracellular flow in different organs. Plays a specific role in embryonic development.
Synonyms: PV-1; FELS; PV1; gp68; DIAR10
Tractability: Antibody: UniProt places it where antibodies can reach, with medium confidence; UniProt predicts a signal peptide or a membrane-spanning region; its Gene Ontology location is reachable by antibodies, with medium confidence; the Human Protein Atlas places it where antibodies can reach. PROTAC: ubiquitination databases record sites on it.
Gene: Protein-coding gene on chromosome 19 (17,351,450 to 17,377,356, reverse strand). Ensembl gene ENSG00000130300.
Subcellular location: Cell membrane; Membrane, caveola; Cytoplasm, perinuclear region
Subcellular location (Human Protein Atlas): Cytosol; Centrosome; Plasma membrane
Gene Ontology:
Molecular function: protein binding; identical protein binding
Biological process: MAPK cascade; positive regulation of cellular extravasation; tumor necrosis factor-mediated signaling pathway; developmental process; regulation of vascular permeability
Cellular component: caveola; cell surface; extracellular exosome; plasma membrane; perinuclear region of cytoplasm
Genetic constraint (gnomAD): Loss-of-function variants: 34 observed, 44.6 expected, observed/expected ratio (o/e) 0.76, 90% interval 0.58 to 1.01. The upper end of that interval is the gene's LOEUF score, 1.01, which puts it in group 4 of 6, group 1 being the genes least tolerant of losing a copy. Missense variants: 574 observed, 616.61 expected, observed/expected ratio (o/e) 0.93, 90% interval 0.87 to 1. Synonymous variants: 241 observed, 247.69 expected, observed/expected ratio (o/e) 0.97, 90% interval 0.88 to 1.08.
Homologues: Orthologues: chimpanzee PLVAP (99% identical), macaque PLVAP (95% identical), dog PLVAP (81% identical), pig PLVAP (80% identical), mouse Plvap (62% identical), rabbit PLVAP (62% identical), rat Plvap (61% identical), zebrafish plvapa (19% identical), zebrafish plvapb (18% identical).
Diseases named in the same sentence as PLVAP in open-access papers:
PLVAP is named in the same sentence as 108 diseases in open-access papers, as found by Europe PMC text mining. Sharing a sentence is not in itself a finding about the gene and the disease. The quoted sentences say what the papers report.
hepatocellular carcinoma (7 papers, 2014 to 2025). A malignant tumor that arises from hepatocytes. "Meanwhile, targeting PLVAP can effectively inhibit tumour growth in cholangiocarcinoma, pancreatic cancer and hepatocellular carcinoma." (PMID 41431249, 2025). "In hepatocellular carcinoma and glioblastoma, PLVAP+ vessels correlate with reduced cytotoxic T‐cell presence." (PMID 41431249, 2025). "Previous study has found that three groups of cancer embryonic cells, including POSTN+ CAF, FOLR2+ TAM, and PLVAP+ EC, have close cellular communication connections in hepatocellular carcinoma." (PMID 39524442, 2024). "For example, RGCC, SPP1 (osteopontin), GPNMB, and APOE are highly expressed in hepatocellular carcinoma (HCC), whereas PLVAP (PV1), CD276 (B7-H3), and ESM1 are predominantly expressed in glioblastoma (GBM)." (PMID 41303611, 2025). "CDH13 was notably a top upregulated gene obtained from the linear modeling of hepatocellular carcinoma (only after GABRD and PLVAP) in an earlier analysis; these observations point to a consistent role for members of the cadherin gene family in cancer progression in gastrointestinal cancers." (PMID 39484215, 2024).
Cirrhosis (6 papers, 2020 to 2025). A chronic disorder of the liver in which liver tissue becomes scarred and is partially replaced by regenerative nodules and fibrotic tissue resulting in loss of liver function. "We and others have confirmed that PLVAP is upregulated on liver endothelium in cirrhosis, and our functional analysis was performed on primary human liver endothelial cells." (PMID 37810232, 2023). "In contrast, both PLVAP+ and VWF+ endothelial cells in the fibrosis and HCC samples were increased compared with the healthy cells, indicating that inflammation as well as angiogenesis happened in cirrhosis and malignant liver." (PMID 33532508, 2021).
diabetic retinopathy (5 papers, 2008 to 2023). "PLVAP expression in BECs only occurs in pathological conditions associated with a compromised barrier function such as cancer, ischemic stroke and diabetic retinopathy." (PMID 37237379, 2023). "However, PLVAP expression in brain and eye barrier endothelia only occurs in pathological conditions associated with a compromised barrier function such as cancer, ischemic stroke and diabetic retinopathy." (PMID 30231925, 2018). "Several studies displayed an involvement of PLVAP in diseases as cancer, traumatic spinal cord injury, acute ischemic brain disease, transplant glomerulopathy, Norrie disease and diabetic retinopathy." (PMID 36781482, 2023). "Correspondingly, PLVAP expression in the BBB and BRB is induced in pathological conditions associated with vascular leakage such as diabetic retinopathy, brain ischemia and brain tumors." (PMID 30231925, 2018). "We did not see an association for the APOL1 and ANKLE1/PLVAP SNPs with baseline Diabetic Retinopathy Severity Score (DRSS) (N = 1,168; P>0.1)." (PMID 37585454, 2023). "This is supported by observations under pathological conditions, where PLVAP is expressed also in the BBB and BRB leading to barrier disruption, such as brain ischemia, cancer, and diabetic retinopathy." (PMID 36781482, 2023). "However, PLVAP expression is also seen at the blood retinal barrier (BRB), but only after insult by factors that induce leakage, such as diabetic retinopathy." (PMID 37585454, 2023).
glioblastoma (5 papers, 2008 to 2026). The most malignant astrocytic tumor (WHO grade IV). "PLVAP is overexpressed in glioblastoma (GBM) both at the mRNA and protein levels but is rarely expressed in normal brain tissues, and this has also been verified in U87 mouse xenograft models." (PMID 36033326, 2022).
glioma (4 papers, 2008 to 2022). A benign or malignant brain and spinal cord tumor that arises from glial cells (astrocytes, oligodendrocytes, ependymal cells). "Elucidating the specific mechanism underlying the function of PLVAP in glioma-associated immunosuppression remains a challenge." (PMID 36033326, 2022). "Gene ontology analysis of PLVAP among gliomas has documented the predominant role of this protein in glioma-associated immunobiological processes and also in inflammatory responses." (PMID 36033326, 2022). "Previous reports have confirmed the significance of plasmalemma vesicle-associated protein (PLVAP) in the progression of multiple tumors; however, there are few studies examining its immune properties in the context of gliomas." (PMID 36033326, 2022). "This work demonstrated the involvement of PLVAP in glioma-associated immune and inflammatory responses, predominantly in the ECS or on cell membranes as extracellular exosomes, membrane components, and integrin complexes." (PMID 36033326, 2022). "PLVAP was remarkably overexpressed in gliomas classified as high WHO grades, particularly among patients with GBM in both cohorts." (PMID 36033326, 2022). "PLVAP is also involved in functional disorder and angiogenic remodeling of the BBB caused by chronic hypoxia in gliomas." (PMID 36033326, 2022). "Secondly, we illustrated the predominant role of PLVAP among glioma-relevant immunobiological processes, inflammatory responses, angiogenesis process, and also ECM organization." (PMID 36033326, 2022). "These inspiring explorations reveal the potential involvement of PLVAP in glioma-connected immunosuppression along with invasion." (PMID 36033326, 2022). "The increase in PLVAP in gliomas was not only due to the increase in endotheliocytes but also to the induction of tumor-related genes that was primarily mediated through Wnt and the Notch signaling pathway." (PMID 36033326, 2022). "PLVAP was markedly upregulated among high grade gliomas, O6-methylguanine-DNA methyltransferase promoter unmethylated subforms, isocitrate dehydrogenase wild forms, 1p19q non-codeletion subforms, and mesenchyme type gliomas." (PMID 36033326, 2022). "This study confirms that overexpressed PLVAP is correlated with some adverse pathology types and angiogenesis process of glioma." (PMID 36033326, 2022). "PLVAP is currently considered a possible therapeutic target for gliomas, glioma-related encephaloedema, and secondary intracranial hypertension." (PMID 36033326, 2022). "For example, a novel recombinant monoclonal anti-PLVAP antibody along with PLVAP-binding antibodies fragments may be used for anti-angiogenic therapy in gliomas." (PMID 36033326, 2022). "Moreover, we further investigated the role of PLVAP in the overall prognosis of glioma patients interconnected with certain major clinical variables such as sex, age, WHO grades, and IDH mutant status." (PMID 36033326, 2022). "Additionally, we identified high-expression PLVAP as a distinct prognostic variable for gliomas, while earlier reports had displayed similar findings in the context of CRC and cholangiocarcinoma." (PMID 36033326, 2022). "Recent studies have confirmed that glioma cells specifically stimulate the expression of PLVAP." (PMID 36033326, 2022). "As a promising antiangiogenic target, PLVAP may serve as a specific molecule via which caveola-mediated pathological processes can be regulated in gliomas." (PMID 36033326, 2022). "Thus, we compared the variance in the mRNA levels of PLVAP among the molecular pathological types of gliomas." (PMID 36033326, 2022). "Here, we determined the correlations of PLVAP high expression levels with neoplasm-infiltrated immunocytes, immunosuppressive processes, unsatisfactory survival, and pernicious pathology types among gliomas." (PMID 36033326, 2022).
glioma (continued). "Based on the recognized clinical significance of these molecular pathological subforms for glioma, glioma patients with elevated PLVAP expression in tumor tissue may possess a high probability of neoplasm invasion, local recurrence, and treatment insensitivity." (PMID 36033326, 2022). "First, we plotted the Kaplan-Meier models using the survival statistics from glioma samples from the TCGA and CGGA sets, and those patients with highly expressed PLVAP exhibited significantly shorter overall survival (OS) time (P < 0.0001)." (PMID 36033326, 2022). "As a glioma endothelial marker gene, PLVAP was deemed to act as a novel biomarker of angiogenesis and BBB integrity in gliomas and was also identified as a possible therapeutic target." (PMID 36033326, 2022). "Meanwhile, PLVAP promoted tumoral neovascularization with high permeability through its interaction with VEGF, and PLVAP knockdown remarkably reduced angiogenesis and tumor growth of gliomas in vivo and in vitro." (PMID 36033326, 2022). "Similar to HCC, PLVAP was highly expressed in vascular endothelial cells of glioma, but not in vascular endothelial cells of normal brain tissue." (PMID 25376302, 2014). "Firstly, our results indicated that PLVAP is related with IDH wild-type, non-codeleted 1p19q, unmethylated MGMT promoter, and mesenchyme subforms of gliomas, which was little known in previous researches." (PMID 36033326, 2022).
liver cirrhosis (4 papers, 2019 to 2025). "Here, we confirmed that PLVAP is indeed upregulated in human liver cirrhosis, but for the first time, to our knowledge, demonstrate a direct correlation with cellular senescence within liver tissue." (PMID 37810232, 2023). "Recent single-cell RNA sequencing studies have highlighted the re-emergence of PLVAP, a marker of fetal liver endothelium largely absent from the adult liver sinusoids, in human liver cirrhosis and HCC." (PMID 37810232, 2023).
viral infection (4 papers, 2018 to 2022). "We found that intranasal infection with PEDV elevated PLVAP expression, suggesting that the viral infection disrupted the integrity of nasal subepithelial microvessels." (PMID 35435723, 2022). "There was up-regulation of PLVAP in hNS1 (human neural stem cell line) cells after 15and 30 min of virus infection." (PMID 30082709, 2018). "PLVAP was found to be co-localized with JEV at SH-SY5Y membrane post 15 and 30 min viral infection and was elevated at membrane protein fraction also." (PMID 30082709, 2018). "Amongst the identified, 5 proteins (PLVAP, GKN3, EXOC8, SRC8, LRAT) were found to be up-regulated at mRNA level in both adult and P10 mouse brain post viral infection." (PMID 30082709, 2018).
celiac disease (3 papers, 2023 to 2025). An autoimmune genetic disorder with an unknown pattern of inheritance that primarily affects the digestive tract. "Interestingly, circulating PLVAP was reported as a serum marker of celiac disease-associated liver injury in humans." (PMID 36674624, 2023).
colitis (3 papers, 2023 to 2025). Inflammation of the colon. "A study conducted in a murine model of dextran sodium sulfate-induced colitis suggested that impairment of the GVB, with a subsequent increase in the endothelial cell-specific plasmalemma vesicle-associated protein (PV1), a marker of vascular permeability, is linked to psychological symptoms." (PMID 40421206, 2025).
hyperlipoproteinemia (3 papers, 2020 to 2024). An elevated concentration of lipoproteins. "As shown in this study, endothelial Gsα knockout mice revealed significant similarity to PLVAP knockout mice, which suffered from edema, anemia, and hyperlipoproteinemia although its severity varied with the background and strain of the mice." (PMID 35721211, 2022).
liver cancer (3 papers, 2018 to 2024). An epithelial or non-epithelial malignant neoplasm that arises from the liver. "Given the observed expression of CEP192 in HPC-like cells and PLVAP+ ECs, we hypothesized that CEP192 may participate in HPC-driven immunosuppressive niche in liver cancer." (PMID 36238304, 2022).
liver fibrosis (3 papers, 2019 to 2023). "Application of scRNA-seq method, TREM2+CD9+ macrophages and ACKR1+PLVAP+ endothelial cells were identified and expanded in liver fibrosis." (PMID 35791909, 2022).
malignant glioma (3 papers, 2014 to 2023). A grade III or grade IV glioma arising from the central nervous system. "In addition to HCC, anti-PLVAP Fab-TF potentially may be used for the treatment of malignant glioma." (PMID 25376302, 2014).
brain ischemia (2 papers, 2008 to 2023). Diminished or absent blood supply to the brain caused by obstruction (thrombosis or embolism) of an artery resulting in neurologic damage. "Considering its association with cancer, traumatic spinal cord injury, transplant glomerulopathy (TG), ischemic brain disease and ocular disease, PLVAP is also investigated as novel therapeutical target, e.g. during cancer therapy." (PMID 36781482, 2023).
brain tumors (2 papers, 2008 to 2022). "In mature brain microvascular endothelial cells forming a functional BBB, no expression of PLVAP was detected, but an increased expression of PLVAP was observed under pathological conditions, such as ischemia or tumors of the brain." (PMID 35633941, 2022).
cholangiocarcinoma (2 papers, 2022 to 2025). A carcinoma that arises from the intrahepatic biliary tree (intrahepatic cholangiocarcinoma) or from the junction, or adjacent to the junction, of the right and left hepatic ducts (hilar cholangiocarcinoma). "In cholangiocarcinoma, PLVAP is upregulated through a DKK1/CKAP4/PI3K‐Akt axis, correlates with micro‐vessel density and poor prognosis." (PMID 41431249, 2025). "Recent reports have verified PLVAP as a practical marker in addition to a prospective treatment targeting lung cancer, cholangiocarcinoma, colorectal cancer (CRC), pancreatic adenocarcinoma, melanomas, liver cancer and brain tumors." (PMID 36033326, 2022).
diabetes (2 papers, 2023 to 2025). "We previously demonstrated that plasmalemma vesicle-associated protein 1 (PV-1) is increased in the gut of Akita mice with a similar duration of diabetes." (PMID 39875729, 2025).
hypertriglyceridaemia (2 papers, 2021 to 2023). "Mutation in the plasmalemma vesicle-associated protein (PLVAP) gene results in a distinct severe form of PLE characterised by hypoproteinaemia, hypoalbuminaemia, and hypertriglyceridaemia." (PMID 36788146, 2023). "While mutations in the plasmalemma vesicle-associated protein (PLVAP) were found to result in a very severe form of PLE characterised by hypoproteinaemia and hypertriglyceridaemia secondary to the deletion of the diaphragms of endothelial fenestrae." (PMID 36788146, 2023). "Ctnnb1OE−EC mice neither showed liver steatosis nor fibrosis, which argue against reduced PLVAP expression as a main driver of isolated hypertriglyceridemia in Ctnnb1OE−EC mice." (PMID 34658910, 2021).
hypoalbuminaemia (2 papers, 2023). "Moreover, humans that own a nonsense mutation in the PLVAP-gene develop similar disease profiles characterized by protein losing enteropathy, hypoproteinemia, hypoalbuminemia, and hypertriglyceridemia, which can lead to a kwashiorkor‐like wasting syndrome and death." (PMID 36781482, 2023). "Thus, the observed hypoproteinemia and hypoalbuminemia in PLVAP-knockout mice are the consequence of increased vascular leakage in fenestrated endothelium." (PMID 36781482, 2023).
idiopathic pulmonary fibrosis (2 papers, 2019 to 2022). Idiopathic pulmonary fibrosis (IPF) is a nonneoplastic pulmonary disease that is characterized by the formation of scar tissue within the lungs in the absence of any known cause. "Anti-PLVAP antibodies have been demonstrated to be effective in regard to treating endotoxin-mediated inflammation, pulmonary fibrosis, kidney disease and certain retinal diseases." (PMID 36033326, 2022). "PLVAP is significantly upregulated in chylous diarrhea-related hepatic damage, pulmonary fibrosis, acute stroke, traumatic spinal cord injury, schizophrenia, and a number of cancers." (PMID 36033326, 2022).
liver disease (2 papers, 2023 to 2025). "Despite this, the regulation and functional role of PLVAP in liver disease is still poorly understood." (PMID 37810232, 2023). "PLVAP may therefore represent an endothelial target that selectively shapes the senescence-mediated immune microenvironment in liver disease." (PMID 37810232, 2023).
macular edema (2 papers, 2018 to 2025). "Besides providing a perspective on PLVAP identification, structure and function, and the regulatory processes involved, we also explore its potential as a novel therapeutic target for vasogenic cerebral edema and retinal macular edema." (PMID 30231925, 2018). "Additionally, we concentrated on several genes presumed to play a role in the pathophysiology of macular edema: VEGFA, VEGFC, EPO, NOS3 (eNOS), PLVAP, and APOE4." (PMID 40455044, 2025).
melanoma (2 papers, 2021 to 2022). A malignant, usually aggressive tumor composed of atypical, neoplastic melanocytes. "Fluorescently labeled antibodies against PLVAP were identified as sensitive targeted imaging tracers for melanoma." (PMID 36033326, 2022). "Interestingly, one report showed that quiescent metastatic melanoma cells in intravascular niches were negative for melanoma markers, and acquired EC features such as the expression of cluster of differentiation 31 (CD31), a protein known to colocalize with PLVAP." (PMID 33671551, 2021).
myocardial infarction (2 papers, 2020 to 2024). Gross necrosis of the myocardium, as a result of interruption of the blood supply to the area, as in coronary thrombosis. "Moreover, droplet-based scRNA-seq was performed on endothelial cells to explore the endothelial heterogeneity of neovascularization after myocardial infarction, and plasmalemma vesicle-associated protein (Plvap) was identified as a novel marker of cardiac neovascularization." (PMID 37322261, 2024).